CCDC201 (coiled-coil domain containing 201)
Gene: Protein-coding gene on chromosome 7 (45,859,994 to 45,873,082, reverse strand). Ensembl gene ENSG00000283247.
Homologues: Orthologues: chimpanzee CCDC201 (97% identical), mouse Ccdc201 (45% identical), rat Ccdc201 (44% identical), mouse Gm14891 (40% identical).